TNF (tumor necrosis factor)
Diseases named in the same sentence as TNF in open-access papers (continued):
Sharing a sentence is not in itself a finding about the gene and the disease.
infection (continued). "Pro-inflammatory cytokines, including tumor necrosis factor-alpha (TNF-α), interleukin-1 (IL-1), and interleukin-6 (IL-6), play crucial roles in initiating and amplifying the immune response by recruiting and activating immune cells at the site of infection." (PMID 37637609, 2023). "Infection control occurs through the activation of immune response cells, such as Th1 cells and macrophages that produce IFN-γ, TNF-α, IL-12, and other cytokines that promote the activation of microbicidal mechanisms and the killing of the parasite by macrophages." (PMID 37255095, 2023). "In contrast, BtCoV-WIV1 infections did not induce any of these responses in the two models, whereas PCoV-GX only induced IL-8, TNF-α, and CXCL-10 in airway organoids." (PMID 36786573, 2023). "Furthermore, knockdown of RACK1 significantly inhibited the secretion of IL-1β and TNF-α as well as the transcription of NLRP3 and IL-1β during PmCQ2 infection." (PMID 37684678, 2023). "Also, cytokines, incorporating tumor necrosis factor (TNF) and Interleukins (IL), can regulate host responses to infection, immune, inflammation, and trauma." (PMID 36969014, 2023). "Secondly, enhanced level of cytokines and chemokines (e.g.IL1B, IL6, CCL5-2, CXCL9-10, and TNFα) in the mother, placenta, and/or neonate was reported in SARS-COV-2 and ZIKV infections." (PMID 37700750, 2023). "At 12 h post-infection, THP-1 macrophages secreted higher levels of TNF-α, IL-6, IL-1β and IFN-γ compared with untreated/uninfected controls, with the Mel˗ conidia group showing significantly higher levels of all four factors compared with the Mel+ conidia group (P < 0.05)." (PMID 37141335, 2023). "In contrast, pro-apoptotic factor TNF was up-regulated in both infections, but not differentially expressed between the infections." (PMID 37513744, 2023). "Extracellular MRP8/14, which is a heterodimeric complex released by phagocytes during infection, acts as an endogenous alarmin that amplifies the TLR4 signaling-dependent inflammatory response by inducing proinflammatory cytokines, such as TNF-α, IL-1β, IL-12 and IL-18." (PMID 37701855, 2023). "In contrast, at the late stage of infection with low viral titer (MOI = 0.1 for 48 h), viral proteins and their downstream signaling can trigger NF-κB activation and TNF expression in MDA5-independent manner, which depends on viral gene expression and replication." (PMID 37956198, 2023). "In the mouse model L. pneumophila-infected macrophages are not producing cytokines, such as tumour necrosis factor (TNF) and interleukin-12 (IL-12), which are necessary to control infection." (PMID 37155695, 2023). "Breakthrough infections led to significantly higher antibody levels in IBD patients under anti-TNF therapy compared to noninfected patients under anti-TNF therapy." (PMID 37766088, 2023). "In contrast, other studies did not report noteworthy changes in TNF serum levels after infections with virulent ASFV isolates belonging to either genotype I (OURT88/1) or genotype II (SY18, HLJ/18)." (PMID 36680273, 2023). "Furthermore, it was recently demonstrated that TNF-α, which is upregulated by SARS-CoV-2, promoted the expression of ACE2 and TMPRSS2, further promoting the infection of cardiomyocytes by SARS-CoV-2." (PMID 37199573, 2023). "Infection with a virulent BoHV-1 isolate (Iowa strain) elicited increased levels of pro-inflammatory TNF, but not IL-1β." (PMID 37112697, 2023). "This coincided with reduced serum levels of pro-inflammatory (IL-1β, TNFα, and KC/GRO) and anti-inflammatory markers (IL-10), increased bacterial killing ability of macrophages, and reduced macrophage infiltration into to site of infection." (PMID 36831019, 2023). "Gene expression of multiple cytokines is raised in the conjunctiva during each stage of disease: IL-1β, TGF-β, TNF-α, IFN-γ, IL-2, IL-4, IL-12 p40 during infection; IL-1β, TGF-β, TNF-α, IL-17A, CCL18 and CXCL5 during active disease, and IL-1β, TGF-β and TNF-α in scarring." (PMID 37862368, 2023).
infection (continued). "As the infection progressed, TNF-α and MCP-1 levels in both primary astrocytes and BV2 cells infected with S. suis strain P1/7 were significantly higher than those of cells infected with the two S. parasuis strains at 18 h and 24 h post-infection." (PMID 37111486, 2023). "A prospective IBD registry revealed elderly (>60 years) persons on anti-TNF had higher rates of serious adverse events (incidence rate ratio [IRR]: 2.06; 95% CI: 1.42, 3.00), and serious infections (61.2 vs. 12.4 infections per 1000 person-years) compared with a younger cohort (<40 years)." (PMID 37674503, 2023). "When very high doses of anti-TNFα therapy were started at the time of the infection, C57BL/6xDBA/2 mice failed to gain control of the infection and succumbed to lethal disease, whereas isotype-treated controls survived with controlled disease." (PMID 37233265, 2023). "In contrast to the neutralization of IFN-γ and TNF or IL-1β, neutralizing IL-6 activity in the post-acute phase of infection did not improve the pathology or fibrotic sequelae post infection." (PMID 38077031, 2023). "Infection of THP-1 cells with fdr mutants resulted in increased IL-1β, TNF-α, and IL-4." (PMID 37764917, 2023). "In the in vitro infection experiment, induction of apoptosis, but not necrosis, with pro-apoptotic TNF peptide in HIV-infected cells slows down HIV-related cell death and reduces HIV viral load." (PMID 36911666, 2023). "In our recent study comparing chronic murine infection caused by a type II (ME-49) strain and a non-archetypal (CK-2) strain (ToxoDB #163), the non-archetypal strain induced higher levels of IFN-γ and TNF-α in brain tissue compared to the archetypal strain." (PMID 38115102, 2023). "Correlation of post-infection sampling time points with plasma cytokine levels from both cohorts showed no clear time-dependent decrease of IL-1β, IL-6, and TNF plasma levels in participants with PASC." (PMID 35732153, 2022). "Serum concentrations of TNF-α, IL-6, and IFN-γ were higher in C3-/- than in wt mice 24 and 48 hrs after infection (–E), indicating that mice genetically deficient in C3 may experience more severe liver damage due to the greater replication of viral load." (PMID 35573780, 2022). "Heightened colonic cytokine levels in the WT-infected group also correlated with significant increases in serum GCSF, IL-1β, IL-3, IL-6, IL-17, CXCL1, CXCL9, MCP-1, TNF-α and TREM at the peak of infection (48-hours), when compared to the TcdA−TcdB−CDT+ and uninfected groups (p< .05)." (PMID 36045589, 2022). "Further, we quantified phosphorylation of p65 by densitometry and our results confirmed that this phosphorylation of p65 is partially rescued by 6 h post infection with Bpm Δhcp1 in the presence or absence of TNF-α." (PMID 35984745, 2022). "Venn diagram analysis showed that among the common DGEs in the 3 h and 12 h infection groups compared with the control group, 11 differential genes were enriched in the NF-κB signaling pathway, including CXCL8, IL-1β, CCL4, IκBα, TNF, NF-κB, CFLAR, PTGS2, TRAF1, PLAU, and IL-1β2." (PMID 35215890, 2022). "Changes in lymphocytes, basophils, mast cells, IgE, TNF-a, IL-1, IL-6, and IL-8 did not significantly differ relative to infection status or disease severity." (PMID 35902827, 2022). "Similar to CRP, the mRNA level of TNF-α in rRGNNV-B2-M1 and rRGNNV-B2-M2 infected zebrafish was also significantly lower than that in wtRGNNV and rRGNNV-infected zebrafish with higher virus titer (1.45 × 106 TCID50/mL and 1.45 × 105 TCID50/mL) infection." (PMID 36016359, 2022). "Therefore, after infection with T. gondii, the levels of IFN-γ and TNF-α increased to resist T. gondii infection." (PMID 36245502, 2022). "Moreover, other inflammatory factors, such as IL-6 and TNF-α, were also found to be upregulated in ECHO 11-infected THP-1 cells and BMDMs, confirming that ECHO 11 infection induces inflammation." (PMID 36026486, 2022).
infection (continued). "Previous studies in a fish model of infection with A. hydrophila demonstrated the expression of RELA gene and the NF-κB pathway that could result in the production of several cytokines such as TNF-α, IL-1β, IL-12, IL-8, IL-6, and IFN." (PMID 35874671, 2022). "In agreement with our transcriptome analysis, we observed significant mRNA increases of pro-inflammatory cytokine genes including TNF, IL-6, and TNFAIP3 starting at 4 h post infection, while increases in IFN pathway genes were only observed at 24 h and only in Calu-3 cells." (PMID 35022513, 2022). "Logistic regression analysis on the results obtained for the training cohort identified three promising combinations of markers to be used to rule-out infection: HBHA- and ESAT-6-induced IFN-γ, HBHA- and ESAT-6-induced TNF-α, HBHA-induced IL-2 and ESAT-6-induced TNF-α." (PMID 35359958, 2022). "Although in WT mice, the TNF-α production was increased after infection statistical significance was not achieved; in IL-32γTg mice, there was significant increase of TNF-α production." (PMID 35097133, 2022). "Within the context of adjuvants used alongside TNF inhibitor treatment, these proposed treatments are meant to aid in infections without triggering an onset of severe inflammation." (PMID 36159650, 2022). "The “integrated” TNF pathway was identified only for the infection group and not for the infection plus rescue." (PMID 35844510, 2022). "Cytokine levels have also a positive correlation between sex the levels of IFNγ were higher in control males, meanwhile, TNF-α and IL-6 were higher in females without infection, indicating that females have a basal proinflammatory profile." (PMID 35335632, 2022). "Pro-inflammatory IL-1β, IL-6, and TNF-α cytokines increased in patients bearing hip prosthetics after infection with coagulase-negative staphylococci." (PMID 35203495, 2022). "In a study from the Czech- Rebulic no increase in infection rate was found in children exposed to anti-TNFα, compared to unexposed infants of non-IBD mothers." (PMID 36120653, 2022). "Both at 6 and 24 h after infection, bacterial burdens, neutrophil recruitment, neutrophil activation (CD11b expression, MPO and elastase production in the BALF), and pro-inflammatory cytokines (IL-1β, IL-6 and TNF) levels were similar in both mouse strains." (PMID 35269409, 2022). "However, infection with LdCen-/- limits the expression of CD200 in CD11c+ dendritic cells, resulting in the reduction in IL-10 and the increase in IFN-γ and TNF-α production by CD4+ T cells." (PMID 35456106, 2022). "The fact that we only observed increased TNFα localised to sites of infection, and not throughout the whole embryo, suggests that oxsr1a knockdown primes cells for NLRP3 activation but does not cause excess systemic inflammation." (PMID 35545295, 2022). "TNF and other cytokines such as IL-12 and IFN-γ are central in the early control of the infection." (PMID 36530876, 2022). "Upon infection with LPS, the activation of PI3K/AKT signaling pathway activates nuclear factor-kappa B (NF-κB) and inhibits protein-1 (AP-1) and ultimately increases the expression of inflammatory cytokines such as IL-6 and TNF-α." (PMID 35295341, 2022). "Moreover, it was observed that the expression of IL-12, IL-6, TNF-α, HLA-DR, and CD40 by monocytes-derived DCs was drastically reduced after infection." (PMID 35720410, 2022). "While TNF is one of the main cytokines operational in iron regulation during infection, early activation of TfR1, independent of IRP, suggests a separate activation pathway for enhancing iron import." (PMID 35862797, 2022). "In experiments using viable pneumococci, myeloid Lkb1 deficiency did not impact inflammatory responses with the exception of TNFα production after infection with the non-encapsulated Spneu D39Δcps strain." (PMID 36096803, 2022). "Consequently, PRV-∆UL13 infection enhanced the induction of IFNB1 and downstream ISGs, as well as the key inflammatory mediators, including IL6 and TNF." (PMID 35891444, 2022).
infection (continued). "The infection elicits significant increases in IFN-γ, TNF-α, CCL2, CCL5, CXCL1, and CXCL2." (PMID 35326323, 2022). "To test this, we next measured changes in the intracellular metabolism of macrophages in the context of thermal injury that also induces a TNFα+ macrophage population, but in the absence of infection." (PMID 35200139, 2022). "Although an 88.2%–96.4% (median 90.0%) reduction in HIVBaL infection of rCD4 was also observed in TNFα-treated LEC cocultures, the difference was not statistically significant, given the small sample size for the LEC cocultures (n = 3)." (PMID 34465136, 2022). "In human macrophages, wildtype MYXV infection triggers IFN-I and TNF through the activation of RIG-I, which may explain the upregulation of a subgroup of cytokine and chemokine genes by wildtype MYXV that are common to ISD treated samples." (PMID 36103568, 2022). "For instance, the components of inflammatory pathways that are major therapeutic targets like NF-κB, TNFα, and the NLRP3 inflammasome are shared across many cell types and mediate cellular processes from cell survival to host defence against infection to chronic inflammatory disease." (PMID 36339576, 2022). "Despite this difference in cytokine gene expression, levels of TNFα & IL-1β in BALF were generally similar for the Hi2019WT and Hi2019ΔlldD strain except for IL-1β levels at 6 h post-infection where lower levels were observed for infections with the mutant strain." (PMID 35085362, 2022). "Both TMEV-susceptible (e.g., SJL/J) and TMEV-resistant (e.g., C57BL/6J) inbred mouse strains mount a strong pro-inflammatory cytokine response within the CNS during the acute phase of infection, for example as shown by increased transcript levels for cytokines IFN-γ, IL-1, IL-6, IL-12p40, and TNF-α." (PMID 35805128, 2022). "TNF-α was only significantly increased at 6 d.p.i; IL-6 was significantly increased at 3 and 6 d.p.i; IFN-γ and NOX2 were significantly increased at 3 and 6 d.p.i, and CD69 showed persistent elevation over the 6 days of infection." (PMID 35930608, 2022). "When analyzing pro-inflammatory cytokine gene expression, we observed a significant increase in gene expression at d7 p.i. of IL-1β and IFNγ with no change of TNF or iNOS expression in p.o. infected mice when compared to i.p. infection." (PMID 35898505, 2022). "Finally, a high number of pro-inflammatory cytokines were up-regulated upon infection, such as CXCL10, CCL5, CXCL11, TNF, CCL3, CXCL8, and IL6." (PMID 35893684, 2022). "In addition, after non-specific Iono/PMA or specific zoledronate stimulation, Vδ2+ T lymphocytes expressed higher levels of TNF-α and IFN-γ in the presence of infection." (PMID 36359845, 2022). "Among different pro-inflammatory cytokines, tumor necrosis factor (TNF) α, one of the predominant cytokines released during inflammation and/or infection, is most often believed to act as an inducer of sperm apoptosis, phosphatidylserine translocation, or DNA fragmentation." (PMID 36060647, 2022). "The treatment of LPS/TNFα and 5Z-7-oxozeaenol (5z7), the inhibitor of TAK1, is used to mimic the effect of Yersinia pathogen infection, since Yersinia species bacteria rely on the effector protein YopJ to block activation of TAK1 and NF-κB pathway toward cell death and inflammation." (PMID 34862482, 2022). "In addition, ELISA results (proinflammatory cytokines IL-6 and TNF-α detected in cell supernatant) showed the downregulation of IL-6 and TNF-α in the MLA and MEM groups compared to the E44 infection group (p < 0.01)." (PMID 36289622, 2022). "During the assessment of the patients on the first day, vital signs (heart rate, blood pressure), infection indicators (WBC, PCT), inflammatory indicators (TNF-α, IL-10, IL-6), CVP, Norepinephrine (NE), oxygenation index (OI), CTNI, and NT-pro BNP were collected." (PMID 35729330, 2022).
infection (continued). "Infection with live SARS-CoV-2 activated the coagulation cascade by promoting the release of endothelial cytokines, including IL-1α, IL-6, and TNF-α, and the expression of endothelial pro-thrombotic markers, such as von Willebrand factor and plasminogen activator inhibitor-1." (PMID 35806421, 2022). "Collectively, these signaling events transcriptionally up-regulate cytokines and growth factors, such as interleukin 1β (IL-1β), tumor necrosis factor α (TNF-α), and granulocyte-macrophage colony-stimulating factor, eliciting innate immune responses against pathogen infection." (PMID 36409895, 2022). "During infection, CopC I55D/F58D/L59D, complemented into the C. violaceum ΔcopC, also failed to block TNF-α-plus-CHX stimulation of the apoptotic program in HeLa cells, evident from the diminished cleavage of caspase-3, caspase-7, and PARP1." (PMID 35446120, 2022). "In Thio-Pmacs, we found that inhibition of C3aR did not affect TNFα or IL-1β secretion, but slightly inhibited IL-6 secretion at 2h, but not 6h post-infection." (PMID 36174103, 2022). "As expected, infection with ETEC significantly (P < 0.05) increased the levels of TNF-α, IL-6, and IL-8 mRNAs compared to no-treatment control and CP9 alone." (PMID 35736372, 2022). "After infection, interleukin-12 (IL-12) is expressed by antigen-presenting cells (APCs) and promotes the differentiation of antigen-specific CD4+ T cells into IFN-γ and TNF-producing Th1 cells, which activate macrophages to kill internalized parasites." (PMID 36290364, 2022). "Third, the latest inflammatory factors, such as IL‐6, IL‐1, tumor necrosis factor alpha (TNF‐α), and the more sensitive infection markers, including procalcitonin, were not included in this study." (PMID 35748095, 2022). "ZIKV (H/PF/2013) infection of microglial cells resulted in the expression of high levels of interferon type I (IFN-α and IFN-β) and type II (IFN-γ), as well as neurotoxic factors with strong proinflammatory effects (TNF-α, IL-1β, IL-6, MCP-1)." (PMID 35371036, 2022). "After 24 h infection, PRV strongly induced NO, IL-6 and TNF-α expression in the BV-2." (PMID 35324841, 2022). "Increased HGF has been found in plasma during infection in both septic and nonseptic patients, where early phase septic patients displayed elevated levels of TNF and IL‐10,24 signifying an active inflammatory response." (PMID 35285058, 2022). "The results also showed low TNF-α production during infection with S. schenckii conidia, and no production during infection with yeasts." (PMID 35628694, 2022). "Similar to their inbred counterparts, outbred SPexp mice had increased proinflammatory cytokines (IL-2, IL-6, TNF-α, and IFN-γ), decreased cellularity in the blood, and an increased frequency of Ag-experienced CD4 and CD8 T cells within PBL 5 d after last infection, as seen in inbred SPexp mice." (PMID 35878936, 2022). "Moreover, both B.1.351 and GD108 induce the S-specific T-cell immune response at the early stage of infection, with higher levels of IFN-γ and TNF-α in macaques infected with B.1.351, whereas there were higher levels of IL-17 in those infected with GD108." (PMID 36069561, 2022). "Our results indicate that infection with WT GBS significantly enhanced the production of IL-1β, MIP-1α, and TNF-α in the uterus, decidua, placenta, amnion, and fetus compared to the uninfected controls (*, P < 0.05 by one-way ANOVA; #, P < 0.05 by Student’s t test)." (PMID 36409087, 2022). "TNF-α, IL-1β, VEGFA, and ICAM-1 mRNA levels in tissues were detected, which were observed to be remarkably upregulated in the DR and DR + Lv-sh-NC groups whereas partially downregulated after Lv-sh-Cx43 infection." (PMID 36120455, 2022). "Another possible explanation for the differential infection risks is that a mechanism independent of TNF-α neutralization is responsible in some of the mAb’s." (PMID 36159650, 2022).